SSU72L2 (SSU72 like 2)
Description:
Protein phosphatase that catalyzes the dephosphorylation of the C-terminal domain of RNA polymerase II. Plays a role in RNA processing and termination.
Synonyms: SSU72P2
Gene: Protein-coding gene on chromosome 11 (4,241,641 to 4,242,706, reverse strand). Ensembl gene ENSG00000284306.
Subcellular location: Nucleus
Gene Ontology:
Molecular function: protein serine/threonine phosphatase activity; RNA polymerase II CTD heptapeptide repeat phosphatase activity; phosphoprotein phosphatase activity
Biological process: termination of RNA polymerase II transcription; mRNA 3'-end processing; mRNA processing; regulation of transcription by RNA polymerase II
Cellular component: mRNA cleavage and polyadenylation specificity factor complex; nucleus
Homologues: Orthologues: tropical clawed frog ssu72 (67% identical), zebrafish ssu72 (67% identical), Drosophila melanogaster Ssu72 (49% identical), Caenorhabditis elegans ssup-72 (46% identical). Paralogues in human: SSU72L1 (99% identical), SSU72L4 (98% identical), SSU72L5 (98% identical), SSU72L3 (96% identical), SSU72L6 (93% identical), SSU72 (71% identical).